MMP9 (matrix metallopeptidase 9)
Diseases named in the same sentence as MMP9 in open-access papers (continued):
Sharing a sentence is not in itself a finding about the gene and the disease.
tumor (continued). "We validated this possibility in G401 cells and the tumour tissues of MRTK and confirmed the high expression levels of MMP2 and MMP9 in MRTK." (PMID 36408277, 2022). "MMP9, one of the matrix metalloproteinases and most commonly involved in the EMT of SCCHN, can promote tumor invasion and metastasis by degrading extracellular matrix (ECM)." (PMID 36050634, 2022). "MMP-2 and MMP-9 can degrade the ECM, greatly change the viscosity and mobility of the tumor, and promote invasion and metastasis." (PMID 35684565, 2022). "PDAC is known to be a hypoxic/fibrotic tumor, which presents rich stroma and secretes proangiogenic factors, namely, VEGF, MMP-9, interleukin-8, and fibroblast growth factor-2." (PMID 35744019, 2022). "Significant suppression of CD163 and CD209 expression and suppression of mRNA expression with subsequent reduction in MMP-9, RANTES, VEGF production (tumor growth factors secreted by macrophages)." (PMID 36140188, 2022). "Compared with the Ctrl or Ctrl+Sh-NC group, tumor tissues derived from the HG or HG + Sh-NC group exhibited increased positivity for Pin1, BRD4, NAP1L1, PCNA, and MMP9, and reduced positivity for P21." (PMID 35461311, 2022). "They reported that MMP-9 secreted by TANs converted the TGF-β precursor into an active form to exert immunosuppression and promote tumor progression in an inducible-colon-tumor mouse model." (PMID 36230676, 2022). "In previous papers, some tumor-promoting genes (like Snail1, Slug, ZEB1/2, MMP2, MMP9, and ADAM12) were found to be modulated by TGF-β." (PMID 35794983, 2022). "The results showed that MMP2 and MMP9 were significantly highly expressed in MRTK tumour tissues compared to adjacent cancerous tissues, and MMP2 and MMP9 were equally highly expressed in G401 cells compared to control HEK293T cells." (PMID 36408277, 2022). "In vivo studies show that IL-17A inhibition at the tumor sites suppressed CD31, MMP9, and VEGF expression in tumor tissues." (PMID 35626056, 2022). "MMP9, VEGF, and CCL4 were found to be employed by neutrophils to promote tumor development, and our study verified them to be upregulated in ccRCC." (PMID 35299868, 2022). "After the activation by NK-derived factors, such neutrophils supported tumor angiogenesis by releasing VEGF and MMP-9." (PMID 35158807, 2022). "MMP-9 was demonstrated to infiltrate BCC and SCC by in situ hybridization in the stromal fibroblasts around the neoplasm and was found in the reactive eosinophils infiltrating the dermis." (PMID 36293148, 2022). "These downstream targets, namely, VEGF and matrix metalloproteinase 9 (MMP9), regulate tumour angio-genesis." (PMID 35052495, 2022). "Low expression of miR-138-5p in tumors leads to overexpression of HOXD11, which induced FN1 transcription and increased MMP2 and MMP9 expression to degrade ECM and promoted tumor metastasis in vivo and in vitro." (PMID 36151071, 2022). "On the other hand, the expression of MMPs (such as MMP9 and MMP3) results in the release of active growth factors, such as VEGF, which indirectly increase the tumor angiogenesis." (PMID 36139552, 2022). "Therefore, MMP2 and/or MMP9 might be involved in tumour cell invasion." (PMID 35954423, 2022). "High TGFβ expression within the tumor microenvironment was also reported as important in the induction of MMP-2 and MMP-9 proteins in both tumor and endothelial cells, promoting invasion and angiogenesis." (PMID 36497429, 2022). "KLF4 overexpression was verified to result in the inhibition of tumour cell migration and invasion by reducing the levels of metastasis-related MMP2, MMP9, and N-cadherin." (PMID 36518312, 2022). "In the HBx‐expressing MHCC97H xenograft tumour tissues, si2R5C treatment decreased the expression of B56γ, upregulated the levels of p‐AKTThr308, p‐AKTSer473, MMP2, and MMP9 in the si2R5C injection group." (PMID 35811356, 2022).
tumor (continued). "Activated MMP-9 can degrade the ECM and basement membrane components, allowing tumor cells to break through the primary site and become invasive and metastatic." (PMID 36497458, 2022). "When correlation analysis was carried out in tumor samples, SLC22A17 was negatively correlated with both LCN2 and MMP9, showing few correlation pairs compared to those obtained for normal samples." (PMID 36211450, 2022). "The tumor cells secrete matrix metalloproteases (MMPs), like MMP2 and MMP9, which helps to degrade the collagen matrix to make a path for invading cells." (PMID 35686673, 2022). "Invadopodia can secret matrix metalloproteinases (MMPs) characterized by MMP2 and MMP9 to remodel the ECM and enhance tumor cell motility 32,33." (PMID 36147460, 2022). "MMP-9 expression and tumor vascularity progressively increase from normal mucosa to OED, indicating an additional pro-angiogenic role of MMPs in early tumor formation." (PMID 36428690, 2022). "Western blotting was used to assess the levels of ENO1, c-Myc, β-catenin, MMP-9, PGAM1, and MMP-13 in SKCM-derived cell lines or tumor tissues from patients with SKCM." (PMID 35925486, 2022). "The interaction of neutrophils and HNSCC/OSCC cells was found to enhance the chemotaxis of neutrophils to the TME and secretion of MMP-9 and CCL4 by neutrophils, triggering further recruitment and aiding tumor progression." (PMID 35784290, 2022). "MMP-9 and HIF-1α expressing neutrophils were shown to be the main tumor-infiltrating cells that promoted angiogenesis and significantly contributed to the NIP pathogenesis." (PMID 35158807, 2022). "In a mouse model of LLC, bone marrow-derived cells transplanted from CD204 KO (knock-out) mice into WT mice enhanced tumor growth and angiogenesis through elevated COX-2, SDF1, VEGF and MMP9 expression in tumor." (PMID 36686729, 2022). "In the invasive tumor group there were two significant correlations: first between MMP-1and MMP-2 expression (rho = 0.306, p = 0.031) and second between TIMP-2 and MMP-9 expression (rho = 0.464, p = 0.001)." (PMID 36551933, 2022). "Thrombospondin (TSP) 1 and platelet-derived PDGF promote tumor invasion and metastasis by upregulating MMP2/MMP9 expression and inducing EMT through the p38 MAPK signaling pathway." (PMID 35936717, 2022). "CA’s mechanism of action involves preventing reactive oxygen species formation, diminishing the angiogenesis of cancer cells, enhancing the tumor cells’ DNA oxidation, and repressing MMP-2 and MMP-9." (PMID 35355732, 2022). "Multiple MMP family members, such as collagenase 1 (MMP-1), gelatinase A (MMP-2), gelatinase B (MMP-9), matrilysin (MMP-7), and membrane-type (MT)-MMPs, have been correlated with tumor progression such as the formation of metastasis and bad prognosis." (PMID 36366531, 2022). "The interrelation of MMPs with the tumor microenvironment is complex, as some of them (MMP-1, MMP-9) are also induced by external carcinogens such as tobacco or betel quid chewing." (PMID 36547091, 2022). "The expression levels of heparinase 1, MMP9, β-catenin, N-cadherin, and PI3K/AKT/mTOR, as well as their phosphorylation levels, which are involved in tumor progression, were reduced after treatment with Gleditsiae Spina." (PMID 35299895, 2022). "Under expression of PTGS2 (READ) and PDGFRA (COAD and READ), over expression of MET & MMP9 (COAD and READ) were observed in the expression analysis using boxplots of genes between normal and tumor samples." (PMID 36110531, 2022). "These reported significantly higher concentrations of mainly MMP-1, MMP-2, MMP-3 and MMP-9, but also of other MMPs in the saliva of patients with OSCC, compared to healthy controls, which were also correlated with the tumor stage." (PMID 36547091, 2022). "Our mechanism studies showed us that proteins facilitating tumor metastasis, including MMP‐2 and MMP‐9, were downregulated by mMNS@Cal." (PMID 35111955, 2022).
tumor (continued). "Mice deficient for IFNβ present an increase in neutrophil infiltration and these cells express higher gene-level expressions of VEGF and MMP9 and CXCR4, a neutrophil tumor-homing factor." (PMID 35626056, 2022). "Further, their data revealed the modulation of tumor invasion and metastasis markers, such as MMP-2 and MMP-9, as well as FAK gene expression in CNE1 cells." (PMID 36015440, 2022). "In conclusion, we identified PTBP1and SLC39A1, and MMP9 and SLC16A3 as tumor specific antigens for LGG and GBM, respectively." (PMID 36307882, 2022). "Anti-tumor: Suppression of tumor growth and angiogenesis via inhibition of COX-2, SDF1, VEGF, and MMP9 expression and down-regulation of JNK/ERK/IκB/NFκB signaling pathway inLLC tumors, as well as inhibition of macrophage polarization and monocyte recruitment." (PMID 36686729, 2022). "As they contain high amounts of MMP-9, they play a major role in shaping the TME of PDAC, mainly by enhancing the invasion of tumor cells, as well as the angiogenesis by inducing VEGF production." (PMID 35205732, 2022). "RT-qPCR experiments were conducted on 22 tumor tissue samples from patients admitted to our clinical department to analyze the expression profiles of ADAM8, MMP9, and miR-181a-5p in GBM tissue." (PMID 35371977, 2022). "However, a study found that genetic deficiency of MMP9 enhanced CAC development and reduced survival in AOM/DSS-treated mice suggesting an anti-tumoral role in CAC in contrast to APC-mutation-driven CRC, where genetic deficiency of MMP9 decreased tumour number by 40% in Apcmin/+ mice." (PMID 36263033, 2022). "EGFR activation in human carcinoma cell lines increases matrix metalloproteinase-9 (MMP-9) activity, which increases cell invasion by facilitating the disintegration of ECM barriers for tumor invasion." (PMID 36081848, 2022). "The anti-HCC effect is related to preventing ROS production, inducing DNA oxidation of cancer cells, reducing angiogenesis of tumor cells, blocking stats, and inhibiting MMP2 and MMP9." (PMID 36277879, 2022). "Matrix metalloproteinase-9 (MMP-9) is a proteolytic metalloenzyme that degrades the central part of the extracellular matrix (ECM) and promotes tumor metastasis." (PMID 35954126, 2022). "A heatmap profiles showed that CTSK, MMP9, CKB, CCL18 and COL6A2 were upregulated in macrophages in tumor tissues." (PMID 36466840, 2022). "In contrast to the controls, the protein expressions of CXCR4, CXCL12, CCR7, CCL21, P-ERK1/2, MMP-9, and MMP-2 in SK-Hep1 cells were significantly increased after transfection of tumor-derived DNA, while the increase was reversed by sinobine hydrochloride." (PMID 35860597, 2022). "The reversion-inducing cysteine-rich protein with kazal motifs (RECK), initially considered a tumor suppressor gene, has been demonstrated to inhibit tumor invasion and metastasis by negatively regulating MMP2 and MMP9." (PMID 35562926, 2022). "In these mice, the lack of LCN2 caused a significant reduction in immune cell infiltration, PanIN, and tumor growth, suggesting that LCN2 in the TME is an important determinant for PDAC progression and patient prognosis, similar to MMP-9." (PMID 35216088, 2022). "During the development of cancer, MMP9 and MMP2 degrade the basement membrane and promote the metastasis of tumor cell to distant tissues and/or organs." (PMID 35959493, 2022). "Examples of MMPs playing significant roles in both settings—trophoblast and tumor invasion—are MMP-2 and MMP-9, both known to be important facilitators of invasion." (PMID 35625802, 2022). "HOXD11 was mediated by miR-138-5p and induced FN1 transcription and increased MMP2 and MMP9 expression to degrade ECM and promoted tumor metastasis in vivo and in vitro." (PMID 36151071, 2022). "In cancer, MMP9 and MMP2 appear to play a role in tumor invasion and angiogenesis and to mediate the tumor microenvironment." (PMID 34980260, 2022).
tumor (continued). "When tumor cells were co-cultured with macrophages (THP-1 cells), expression of LCN2 and MMP-9 in ADAM8 KO cells was induced, suggesting that macrophage signaling can overcome ADAM8-dependent intracellular signaling in PDAC cells." (PMID 35216088, 2022). "MDSCs are capable of boosting angiogenesis and promoting tumor neovasculature, through the production of high levels of MMPs, such as MMP2, MMP8, MMP9, MMP13, and MMP14." (PMID 36419156, 2022). "In turn, the generated O2 improved the cytotoxicity and anti-tumor migration effect of CS-1 by downregulating HIF-1α and MMP-9 levels." (PMID 36424589, 2022). "Particular inhibitory antibodies to MMP-9 and MMP-14 have been developed and shown to be effective in inhibiting tumor growth and metastasis, but their clinical efficacy is currently uncertain." (PMID 36700222, 2022). "These cells shifted from anti-tumor IFN-γ production to an increase in pro-inflammatory cytokine production, such as MMP9, promoting aberrant neo-angiogenesis." (PMID 36294305, 2022). "It has been reported that IL-6 can enhance tumor angiogenesis and metastasis either directly or by inducing the expression of well-known angiogenic and metastatic molecules such as VEGF, MMP2 and MMP9 in cancer cells." (PMID 35300689, 2022). "By contrast, the circBRWD3 knockdown tumor model exhibited opposite phenotypes with a decreased level of E-cadherin and increased levels of N-cadherin, Vimentin, MMP2, and MMP9." (PMID 36443711, 2022). "Ionizing radiation has been shown to alter tumor microenvironment by interfering cell-cell communication and inducing stromal cells to secrete various cytokines, ɑ-SMA, MMP-2 and MMP-9, which can potentially promote the metastasis of cancer." (PMID 36084485, 2022). "Matrix metalloproteinase-9 (MMP-9) and tissue inhibitors of metalloproteinase-1 (TIMP-1) play important roles in the proliferation and metastasis of NB tumor cells." (PMID 35847358, 2022). "MMPs: MMP activity is shown to be significant for invasion because MMP-2, MMP-9, and MT-MMPs can together degrade almost all types of ECM; they are specifically activated in tumor tissues, and their activation correlates with a poor prognosis and invasion." (PMID 35053605, 2022). "MMP-9 is a pivotal enzyme that involved in ECM degradation, and its overexpression is closely related to tumor metastasis." (PMID 35954126, 2022). "Thereafter, two allosteric mouse MMP9 mAbs, AB0041 and AB0046, were shown to inhibit tumour growth and metastasis in a xenograft model of colorectal carcinoma." (PMID 35158891, 2022). "COX-2(+) TAMs promoted the expression of MMP-9 and EMT phenotype in breast cancer cells by activating AKT signaling, thus promoting tumor cell invasion and metastasis." (PMID 35251963, 2022). "HIF-1α also induces matrix metalloproteinase (MMP) expression, such as gelatinases MMP-2 and MMP-9, which degrade the ECM, assisting in tumor cell migration." (PMID 35163668, 2022). "Important gene-products of the NF-κB pathway involved in the regulation of tumor invasion and metastasis are uPA, MMP-2 and MMP-9." (PMID 36015440, 2022). "Immune blot results showed that MMP2, MMP9, and MMP13 (migration marker proteins) expression decreased in tumor tissues of anti‐Chi3L1 antibody‐treated mice." (PMID 34861103, 2022). "IHC was used to detect the expression of NF-κB, MMP9, MMP2, and TIMP-2, which are the four key targets for tumor migration and invasion." (PMID 35770085, 2022). "More importantly, western blot and tumor immunohistochemical staining assays demonstrated decreased expression of MMP-2, MMP-3, and MMP-9 in the primary 4T1 tumor after D-NPBB94/C-NPBB94 treatment, which further confirmed its excellent therapeutic activity." (PMID 35440570, 2022). "The arrival of IL-6 also enhances breast CSC migration, promotes tumor growth and metastasis, and induces angiogenesis by inducing the expression of proangiogenic molecules, such as VEGF, MMP2 and MMP9." (PMID 36497411, 2022).
tumor (continued). "Results support that TGF-β, MMP9, VEGF, and CCL4 are all significantly highly expressed in tumor samples." (PMID 35299868, 2022). "Proteolytic enzyme MMP2 and MMP9 facilitate cell invasion and migration by degrading the extracellular matrix (ECM), thereby allowing the invasion of tumor cells into adjacent tissues and the subsequent migration of cells into circulation." (PMID 35889537, 2022). "In vivo, DCH inhibited tumour growth in mice, downregulated the expression of MMP2 and MMP9, and partially reversed EMT." (PMID 36408277, 2022). "One is a tumor-promotive type that produces inflammatory and angiogenic molecules (ROS, VEGF, FGF2, MMP9, IL8, etc.), which induce genetic instability, DNA damage, angiogenesis, and EMT of tumor cells." (PMID 36211375, 2022). "MMPs, like MMP-2 and MMP-9, play a role in ECM degradation and are highly expressed in carcinomas to promote tumor angiogenesis and consequent cancer cell invasion and metastases." (PMID 36185289, 2022). "Further, we found that gene expression of MMP9 and IGF2BP2 was positively correlated with levels of several APCs, which processed tumor antigens and presented them to CD8+T cells." (PMID 36569935, 2022). "In turn, COX2-dependent release of MMP-9, vascular endothelial growth factor (VEGF), and fibroblast growth factors (FGF) support tumor vascularization and progression." (PMID 35558554, 2022). "The cytokine activated NK cells then reduce their MMP-9 and VEGF secretions at tumor sites, which further transforms the pro-tumor microenvironment to an anti-tumor one." (PMID 33456579, 2021). "Among the different MMPs, MMP-9 and MMP-2 belong to a family of zinc-dependent endo-peptidases which are secreted by stromal and tumor cells as inactive zymogens, and then activated following the cleavage of the pro-domain peptide into their active form." (PMID 34885656, 2021). "By performing in vitro experiments, LINC00963 was found to promote CRC cell proliferation, cycle progression, tumor growth, and up-regulated the expressions of MMP-2 and MMP-9." (PMID 33536018, 2021). "Mechanistically, both miRNA-34a and miR-200c directly target HIF1-α and subsequently downregulate VEGFR, MMP9 and CXCR4, although combined miRNA-34a and miR-200c delivery suppresses mouse xenograft tumor development as effectively as individual delivery." (PMID 33673143, 2021). "Transplanted tumor tissue samples were taken for hematoxylin and eosin (HE) staining, and the expression of VEGF, HSP90, HIF-1α, and MMP9 was evaluated via reverse transcription-quantitative PCR or immunohistochemistry." (PMID 34825004, 2021). "For example, a conjugated polymer nanoplatform modified by matrix metalloproteinase 9 (MMP9) cleavable linker allowed foreign antigen to be delivered and conditionally released into the local tumor site." (PMID 34575414, 2021). "Correspondingly, serum CTX-1 level and the expression of osteoclast signature genes Acp5, Ctsk, Mmp9, and Nfatc1 in mice bearing SCP28/Sh-miR-21 tumors were comparable with tumor-free mice." (PMID 33391543, 2021). "Heparanase not only enhances tumor metastasis but is also involved in the regulation of multiple proteins that promote the aggressive biological behavior of tumor, including VEGF and MMP-9 3-6." (PMID 34220326, 2021). "Quantitatively, greater than 60% of MMP9 expression overlapped with PRISM-positive cells in acidic areas close to the tumor-stroma interface, where hallmarks of tumor invasion are enriched." (PMID 34267368, 2021). "They produce many different cytokines, such as MMP9, C-X-C motif ligand 8 (CXCL8), and IL-10, which can induce tumor growth and development." (PMID 34335834, 2021). "Interestingly, the increased expression of MMP9 could reduce tumor purity." (PMID 33656546, 2021).